GFAP (glial fibrillary acidic protein)
Diseases named in the same sentence as GFAP in open-access papers (continued):
Sharing a sentence is not in itself a finding about the gene and the disease.
dementia (continued). "Moreover, in a study on a well-documented UK cohort, GFAP and NfL levels were evaluated in a dementia-free population after adjustment for multiple confounders that may affect protein expression levels (e.g., age and sex)." (PMID 39125924, 2024). "Furthermore, the plasma biomarkers GFAP and NfL may also contribute to the eventual onset of dementia by affecting Rad during this longitudinal process." (PMID 38711474, 2024). "Furthermore, we suggest that plasma GFAP may be a potential biomarker for predicting the progression of MCI to dementia in PD." (PMID 36759508, 2023). "The addition of GFAP could differentiate between the risk of all-cause dementia and the risk of depression among individuals without dementia." (PMID 37951931, 2023). "A (not shown) regression model including a combination of all biomarkers and assessing the association of such combination with dementia risk did not add informative value to the model including the combination of persistent SCC with high GFAP values (OR 2.40; 95%CI 1.16–4.96, p-value 0.0178)." (PMID 37951931, 2023). "However, in the PD–MCI group (n = 68), no significant predictive effect of CSF GFAP on the risk of dementia was found (p = 0.597)." (PMID 37475029, 2023). "Thus, it is conceivable that caspase-6 cleavage of GFAP might add valuable information for the diagnosis and/or prognosis of dementia." (PMID 31693684, 2019). "Thus, we determined whether cortical astrogliosis occurs in PD, whether it is related to dementia, and whether this is reflected by the presence of glial fibrillary acidic protein (GFAP) and vimentin in cerebrospinal fluid (CSF)." (PMID 22577599, 2012). "For the controls versus dementia (FTD) comparison, NfL had the highest AUC value (AUC: 0.89 [95% CI: 0.81–0.98]), and GFAP was the only other marker which showed significant discriminatory performance between the two groups (AUC: 0.75 [95% CI: 0.63–0.88])." (PMID 40551285, 2025). "Higher preoperative blood NfL and GFAP levels independently predicted POD after adjusting for age, sex, dementia, frailty, and Interleukin-6 (Odds Ratio, OR: 3.21, 95% Confidence Interval, CI: 1.26-8.21, and OR: 3.66, 95% CI: 1.38-9.68, respectively)." (PMID 40354379, 2025). "Compared to participants who were Aβ−, those who were Aβ+ were older; had a lower body mass index; had greater rates of dementia and carrying APOE ε4; had lower MMSE and CDR scores; and had greater p‐tau217, p‐tau181, and GFAP levels." (PMID 39877979, 2025). "In The Translational Biomarkers in Aging and Dementia (TRIAD) study, plasma GFAP levels were precise in capturing the brain pathology so that it was possible to discern between preclinical AD, clinical AD, and cognitively unimpaired Aβ-negative individuals." (PMID 41002922, 2025). "From our analysis, the increase of p-tau217, NfL and GFAP in the MCI and dementia groups, compared to the CU group, aligns with current biomarker evidence." (PMID 41282064, 2025). "For plasma GFAP, three group comparisons survived FDR correction: levels were lower in MCI Aβ− compared to MCI Aβ+ and AD, and also lower in the “Other dementias” group compared to MCI Aβ+ and AD." (PMID 40785395, 2025). "GFAP and NFL are both markers of neuroinflammation and potential biomarkers for early diagnosis of cognitive impairment and dementia." (PMID 41369364, 2025). "Compared to patients with aMCI and mild dementia (CDR = 0.5–1), those with moderate-to-severe dementia (CDR = 2–3) had higher levels of NfL (p = 0.013) and GFAP (p = 0.020)." (PMID 40181481, 2025). "Plasma NfL and glial fibrillary acidic protein (GFAP) levels were found to be higher in Lewy body dementia (DLB and Parkinson’s disease dementia) compared to controls but lower compared to AD." (PMID 38961441, 2024). "Just like GFAP, NFL is a promising biomarker of neurodegeneration in MS, dementia, TBI, amyotrophic lateral sclerosis (ALS) and other neurological diseases." (PMID 38580905, 2024).
dementia (continued). "No significant publication bias was identified using funnel plots (eFigure 9, a, c, and d) or the Egger test for any other GFAP meta-analysis (AD continuum vs CU p = 0.1835, MCI-AD vs CU p = 0.9817, AD dementia vs MCI-AD p = 0.4335)." (PMID 38986050, 2024). "The concentration of GFAP increased in the CSF of patients with neurodegenerative diseases, particularly Creutzfeldt–Jakob disease (CJD) and dementia." (PMID 38216970, 2024). "Based on linear regression with histopathological and gene expression data, GFAP and IBA1 levels and GPNMB gene expression positively contributed to the interaction of tau with Aβ in non-dementia cases, replicating the results of the network analysis." (PMID 39554095, 2024). "In summary, we detected significant interactions of NfL and GFAP with AD PRS, in relation to dementia incidence, suggesting potential for personalized dementia prevention and management." (PMID 39586964, 2024). "In general, P‐tau181 and GFAP showed the opposite, levels were higher in the Aβ+ groups (SCD, MCI, AD‐dementia) compared to the Aβ− groups (SCD, MCI)." (PMID 39096164, 2024). "Plasma GFAP concentrations were significantly raised in both acute TBI (1280% increase, 95%CI 548–2830, P < 0.001) and dementia (53.1% [1.45–131], P = 0.042), compared with healthy controls." (PMID 38903933, 2024). "While many studies have demonstrated the potential of NfL and GFAP, most of them have focused on predicting progression from MCI to dementia, whereas only a few studies have investigated the pathologic substrate of MCI defined according to AD biomarkers." (PMID 37723371, 2024). "During astrogliosis or brain-related injury, GFAP is excreted into the circulation, thus being a good biomarker of traumatic brain injury (TBI), MS, dementia, brain tumors, and other neurological diseases." (PMID 38580905, 2024). "We investigated the interaction between GFAP or IBA1 and Aβ, stratifying the analysis by the dementia status and across four brain regions." (PMID 39554095, 2024). "Because NFL and GFAP are non‐specific markers of neuronal injury, further work needs to be done to tease out their utility of VCID in the presence of other dementia etiologies." (PMID 37932910, 2024). "Our results support that plasma GFAP has potential value for distinguishing patients with PDD, and predicting MCI-to-dementia conversion in PD." (PMID 36759508, 2023). "Throughout the whole Alzheimer’s continuum, we observed that plasma GFAP and p-tau181 continued to increase, while plasma NfL levels plateaued during the MCI+ and AD dementia phases." (PMID 36750875, 2023). "We measured the levels of plasma GFAP by Simoa in 60 patients with PD with normal cognition, 63 with mild cognitive impairment (PD-MCI), 24 with dementia (PDD) and 15 healthy controls." (PMID 36759508, 2023). "ROC curve analysis revealed that plasma GFAP allowed a reliable differential diagnosis between PDD and PD-NC (AUC = 0.79), PD-MCI (AUC = 0.74) or PD with non-dementia (including both PD-NC and PD-MCI, AUC = 0.77)." (PMID 36759508, 2023). "Another review mentioned that blood GFAP was useful as an additional marker for the early detection and prediction of the time course of AD and as a biomarker to predict MCI-to-dementia conversion." (PMID 37174709, 2023). "Plasma concentrations of p-tau217, GFAP, and NfL were already increased in participants with DS-CS compared with non-DS siblings and further increased in those with DS-MCI and DS-dementia (eFigure 3 in the Supplement)." (PMID 35789365, 2022). "In addition, GFAP might be a prognostic biomarker to predict incident dementia." (PMID 36351888, 2022). "Conversely, PD patients with white matter alterations and concomitant dementia had significantly fewer CYP27B1 positive astrocytes in the cortex, despite the total GFAP positive cells were unchanged." (PMID 35166042, 2022).
dementia (continued). "The present study examined GFAP, a putative blood‐derived marker for ADRD, among participants free of prevalent dementia at baseline across four longitudinal community‐based cohorts." (PMID 36056631, 2022). "CSF levels of glial fibrillary acidic protein (GFAP) and chitinase-3-like protein 1 (YKL-40), biomarkers of astrocyte reactivity, are consistently elevated in the dementia phase of AD, and in some other brain disorders such as multiple sclerosis." (PMID 35948658, 2022). "Longitudinal GFAP slopes for Aβ-positive and MCI who progressed to dementia (AD or other) were significantly steeper than those for Aβ-negative (p = 0.007) and stable MCI (p < 0.0001), respectively." (PMID 33773595, 2021). "These dementia-specific HCit-containing proteins include brain acid soluble protein 1 (BASP1), spectrin alpha chain 1 (SPTAN1), and glial fibrillary acidic protein (GFAP)." (PMID 28865468, 2017). "Retinal GFAP+ and vimentin+ macrogliosis and IBA1+ microgliosis findings suggest that glial activation and process hypertrophy emerge early along the AD continuum (in MCI due to AD), followed by overt glial proliferation in established AD dementia." (PMID 41571675, 2026). "In our analysis, GFAP was only predictive of incident delirium in our full proteomic set, not in the dementia-free population." (PMID 41286463, 2026). "In this group, we also observed a weak negative correlation between time to dementia and GFAP (Beta = −0.01, P=4.6e-02)." (PMID 40061357, 2025). "GFAP levels were significantly increased in AD patients compared to patients without dementia, suggesting that blood GFAP concentrations rose at a higher rate in people who would go on to develop AD." (PMID 40806404, 2025). "Among participants without incident dementia, APOE4 remains significantly associated with GFAP (Beta = 0.047, P = 5.5e-21), albeit with a smaller effect." (PMID 40061357, 2025). "There was a significant rise in plasma levels of GFAP, p‐tau217, NfL, apolipoprotein E (APOE) ε4 prevalence, AV45‐PET positivity, and global AV45‐SUVR from the CN group to the MCI group and then to the dementia group, while hippocampal volumes significantly decreased." (PMID 41376134, 2025). "Subsequent studies should directly compare AD with non-AD dementias to clarify the discriminative capacity of CSF GFAP." (PMID 40943059, 2025). "The current study demonstrates that elevated plasma levels of VAMP2 as well as GFAP correspond to lower synaptic density within distinct regions in the brains of older adults without dementia." (PMID 40620474, 2025). "The effect of APOE4 on GFAP is also observable in midlife among participants without incident dementia." (PMID 40061357, 2025). "First, several circulating protein markers potentially relevant to dementia, for example, GFAP and GDF-15, were not assayed in ELSA." (PMID 40092369, 2025). "Plasma GFAP levels in MCI-AD cohorts were 300 pg/mL, IQR 232–433 pg/mL, and p < 0.0001, and these levels increased to 360 pg/mL, IQR 253–414 pg/mL, and p < 0.01 in MCI-AD cohorts developing dementia during 3.9 ± 2.6 years follow-up period." (PMID 41002922, 2025). "The main finding of the present study was that patients with CKD stages 3 and 4, without a diagnosis of cerebrovascular disease or dementia, had elevated plasma concentrations of NfL, p-Tau231 and GFAP compared with controls with normal mGFR." (PMID 40346521, 2025). "At baseline, the levels of CSF GFAP were increased in the hyposmic group, but these levels did not predict conversion to dementia." (PMID 40839564, 2025). "Carriers of APOE4 allele showed greater GFAP levels starting in middle age and the effect sizes are greatest in homozygous APOE4 carriers in both incident dementia and non-dementia groups." (PMID 40061357, 2025).
dementia (continued). "In this cohort study, compared with non–APOE4 carriers, neurodegenerative serum biomarkers of t-tau, NfL, and GFAP were associated with lower baseline cognitive function levels and a faster cognitive decline rate among APOE4 carriers without dementia." (PMID 40332937, 2025). "P-tau217, NfL and GFAP showed a stepwise increase from CU to MCI and Dementia." (PMID 41282064, 2025). "Although not AD-specific, GFAP has demonstrated more pronounced elevations in plasma of AD patients than in other dementia types such as frontotemporal dementia (FTD), DLB or vascular dementia." (PMID 40087672, 2025). "It has been shown that GFAP level in individuals without dementia correlates with amyloid burden, and those who are amyloid-positive are linked with neuroimaging biomarkers." (PMID 40867161, 2025). "By setting the time of dementia diagnosis (for those with dementia) or time of end of follow-up (for those without dementia) as 0-time mark, we discerned notable disparities in the expression levels of GFAP and NfL up to 15 years before diagnosis." (PMID 38735950, 2024). "We show clear differentiation of the acute TBI group using finger-prick GFAP and NfL, and a non-significant trend towards separation in the dementia group." (PMID 38903933, 2024). "We evaluated associations between plasma biomarkers commonly studied in Alzheimer's (p‐tau181, GFAP, and NfL), clinical diagnosis (clinically normal, amnestic MCI, amnestic dementia, or non‐amnestic MCI/dementia), and Aβ‐PET in Hispanic and non‐Hispanic older adults." (PMID 37671801, 2024). "We hypothesized that a combination of the current key plasma biomarkers Abeta42/40, P‐tau, GFAP, and NfL can aid in (early) AD, FTD, or DLB diagnosis and in differential diagnosis of AD versus FTD or DLB in the daily clinical dementia practice." (PMID 39096164, 2024). "Nevertheless, as of now, there has been no research validating the relationship between GFAP and NfL with incident dementia in a large-scale population." (PMID 38735950, 2024). "In an investigating study of 818 patients, the concentrations of blood GFAP are reported to be consistently increased in a stepwise pattern from preclinical AD, through mild cognitive impairment (MCI) to AD dementia compared to cognitively unimpaired (CU) individuals." (PMID 38216970, 2024). "Participants with MCI who progressed to dementia due to probable AD during follow-up had higher baseline plasma concentrations of pTau181, NfL, and GFAP compared to non-progressors." (PMID 36937522, 2023). "Furthermore, we investigated the predictive value of plasma GFAP, NfL, Tau and pTau181 for MCI to dementia conversion in PD." (PMID 36759508, 2023). "A combination of using plasma tau phosphorylated at threonine 181 (p-tau-181), neurofilament light chain (Nfl), and glial fibrillary acidic protein (GFAP) for the discrimination of AD, frontotemporal dementia, and dementia with Lewy bodies, has been recommended." (PMID 36982820, 2023). "However, longitudinal analyses performed with the community-based cohort showed that the combination of SCC with APOE ε4 and GFAP could have the potential to contribute to the differentiation between future risk of all-cause dementia and risk of depression in the absence of dementia." (PMID 37951931, 2023). "Plasma GFAP at baseline had a high accuracy for separating patients with stable MCI and MCI to dementia conversion (AUC = 0.90) after an average follow-up of 4.1 ± 2.3 years, with a sensitivity of 90% and specificity of 81% at an optimal cut-off of 100.2 pg/mL." (PMID 36759508, 2023). "One study detected elevated GFAP levels in PD patients with dementia compared with those without cognitive impairment or HCs, whereas another study found that 11C-BU99008 PET cannot differentiate patients with Parkinson’s disease dementia from HCs." (PMID 37932720, 2023).
dementia (continued). "Our study is one of the few studies examining plasma p-tau181/NfL/GFAP and cognitive function longitudinally, and one of the first to do so in an aged cohort without dementia over an ∼10-year period." (PMID 37180996, 2023). "Of the biomarker values that did not undergo correction, YKL40, GFAP, NfL, neurogranin, pTau, and tTau were all increased in patients with AD-dementia or MCI who were A+ compared with CU individuals and patients with MCI who were A−." (PMID 36709293, 2023). "Circulating GFAP levels were assayed using a Simoa HD‐1 analyzer in 4338 adults without prevalent dementia from four longitudinal community‐based cohort studies." (PMID 36056631, 2022). "However, other studies have reported a link between plasma GFAP level and progression from MCI to dementia." (PMID 36351888, 2022). "While GFAP levels in blood and CSF are associated and correlated to amyloid pathology and related to clinical disease severity, GFAP might be a potential biomarker of other types of dementia because astrocytes are not the foremost cell type specific to AD pathophysiology." (PMID 35453600, 2022). "In addition, we saw increased astrocyte reactivity, as indicated with glial fibrillary acidic protein (GFAP) immunolabelling, in those with AD and dementia relative to mismatch cases." (PMID 34963475, 2021). "Even though previous studies suggest that blood GFAP levels are elevated in AD and can identify an amyloid-PET positive status, only one study has measured GFAP in cognitively normal subjects followed over time for conversion to dementia (of any kind)." (PMID 33773595, 2021). "The first aim of this study was to assess the ability of glial (YKL-40, S100B, GFAP) and neurodegeneration (NFL) markers in CSF to discriminate between different CSF profiles (AD and non-AD) among subjects at the symptomatic pre- and early stages of dementia." (PMID 32753068, 2020). "Several dementia-specific citrulline residues were also identified in soluble proteins previously categorized as pro-immunogenic, which include the receptor P2X7, alpha-internexin, GFAP, CNP, MBP, and histones." (PMID 28865468, 2017). "We used immunohistochemistry (IHC) on both fresh frozen and formalin fixed paraffin embedded (FFPE) tissue to stain and quantify proteins marking dementia-related pathologic findings, including pTau, Aβ, α-synuclein (Lewy bodies), and pTDP-43, as well as microglia (IBA1) and astrocytes (GFAP)." (PMID 29120328, 2017). "PCNA+ profiles were never observed in mature neurons or GFAP+ astrocytes, indicating that these cell types do not proliferate or reenter the cell cycle during dementia or AD." (PMID 25215243, 2014). "The positive reaction for GFAP was confirmed by Western blotting demonstrating different bands and different concentrations of GFAP in brain tumoural sites, compared with positive (dementia cases) and negative control." (PMID 23638625, 2013). "Additionally, serum GFAP shows a stronger negative correlation with mini‐mental state examination scores compared to CSF GFAP in a cohort of patients with different types of dementia." (PMID 39289040, 2025). "One study found an association between GFAP and conversion to MCI, but no to dementia." (PMID 40839564, 2025). "All of these studies reporting non-specific changes in blood GFAP and NfL levels as markers of early neuroinflammation and neuronal damage in different types of dementia, including AD and FTD, promote the research of a new marker able to discriminate between these pathologies." (PMID 39125924, 2024). "For GFAP, a significant positive contribution to the interaction was observed in the hippocampus of both the dementia and no-dementia groups (HIP, β = 43.59, p = 0.022 and β = 24.852 and p = 0.001, respectively) and in the temporal neocortex of the no-dementia group (TCx, β = 13.873 and p < 0.001)." (PMID 39554095, 2024). "GFAP may also hold potential as a biomarker for other types of dementia since astrocytes are not specific to AD pathophysiology." (PMID 38352136, 2024).